SOX2 (SRY-box transcription factor 2)
Diseases named in the same sentence as SOX2 in open-access papers (continued):
Sharing a sentence is not in itself a finding about the gene and the disease.
aniridia (2 papers, 2014 to 2022). Aniridia is a congenital ocular malformation characterized by the complete or partial absence of the iris. "To summarize, within the 10-years post-COMET, the ocular surface of this patient suffering from aniridia revealed the coexistence of areas comprising oral mucosa tissue (SOX2+/K13+) and conjunctival epithelium (presence of goblet cells and K13+)." (PMID 35628593, 2022).
Anosmia (2 papers, 2023 to 2025). An inability to perceive odors. "The association of anosmia and SOX2 variation highlights the possibility for a role of SOX2 in olfactory neurogenesis in humans." (PMID 36602867, 2023).
atherosclerosis (2 papers, 2023 to 2025). A disease characterized by the build-up of fatty material and calcium deposition in the arterial wall resulting in partial or complete occlusion of the arterial lumen. "Taken together, the downstream genes of ARL4C, including ABCA1, ALDH1A3, ARF6, ENHO, FLNA, LRP6, OSBPL5, Snail2, and SOX2 play an important role in atherosclerosis." (PMID 40176913, 2025). "The pro-atherosclerosis or anti-atherosclerosis effects of many regulatory genes, such as FLNA and SOX2, depend on their location." (PMID 40176913, 2025).
B-cell lymphoma (2 papers, 2017 to 2023). "In accordance with these findings, the expression of stem cell markers (NANOG and SOX2) was significantly higher in B-cell lymphoma cells survived after phenylbutyrate and doxorubicin treatment than control cells." (PMID 27911272, 2017).
benign prostatic hyperplasia (2 papers, 2019 to 2025). A non-cancerous nodular enlargement of the prostate gland. "In summary, SOX2 is primarily expressed in basal cells of normal and benign prostatic hyperplasia tissues, where it plays a role in maintaining the structural organization and self-renewal of prostate glands." (PMID 40821114, 2025). "In normal and benign prostatic hyperplasia tissues, SOX2 is predominantly expressed in basal cells." (PMID 40821114, 2025).
bladder transitional cell carcinoma (2 papers, 2015 to 2023). The most common morphologic subtype of urinary bladder carcinoma (over 90% of cases). "Furthermore, this study also demonstrated that the level of SOX2 was slightly elevated in the urine samples from individuals exposed to arsenite in Bangladesh and in the urine samples of individuals diagnosed with urothelial bladder cancer." (PMID 37298099, 2023).
brain injuries (2 papers, 2019 to 2021). "Sox2 can enhance the ability of differentiation of BMSCs into neurons and other cells and accelerate the recovery of motor function of rats with traumatic brain injury." (PMID 32922911, 2019). "In turn, mutations of other transcription factors (e.g., PIT-1/POU1F1, PROP-1, LHX3, SOX2, SOX3, OTX2 and HESX1) lead to congenital MPHD, while hypothalamic-pituitary tumours (e.g., craniopharyngiomas), their treatment regimens or traumatic brain injuries result in acquired MPHD." (PMID 34445772, 2021).
breast ductal adenocarcinoma (2 papers, 2018 to 2024). A breast carcinoma arising from the ducts. "All breeder females developed breast ductal adenocarcinomas and had median survival times close to those of Sox2-Cre+ mice, thus confirming that the effect of RRAS2 overexpression is breast epithelium-intrinsic." (PMID 38987766, 2024).
carcinoma in situ (2 papers, 2010 to 2019). "In sharp contrast, SOX2 positive expression was mainly nuclear and evident in all normal bronchial epithelia (n = 52), all four alveolar bronchiolization structures and in all (n = 32) but one cases of dysplasia and carcinoma in situ representing the sequence of SCC pathogenesis." (PMID 20161759, 2010).
CHARGE syndrome (2 papers, 2014 to 2022). CHARGE syndrome is a multiple congenital anomaly syndrome characterized by the variable combination of multiple anomalies, mainly Coloboma; Choanal atresia/stenosis; Cranial nerve dysfunction; Characteristic ear anomalies (known as the major 4 C's). "Previously, we showed that CHD7, which is linked to CHARGE syndrome, directly interacts with SOX2, which in turn is linked to AEG syndrome." (PMID 35615634, 2022). "CHARGE syndrome patients exhibited mutations in the Chd7 gene, the product of which acts as a Sox2 transcriptional cofactor." (PMID 25309446, 2014). "Recent evidence has shown that Sox2 has been indirectly associated with defects that are characteristic of the CHARGE syndrome, a human neurocristopathy." (PMID 25309446, 2014).
chordoma (2 papers, 2022 to 2025). Chordomas are rare malignant tumors arising from embryonic remnants of the notochord in axial skeleton. "The results revealed that high levels of RAB3B, as well as Nanog, Oct4, Sox2, and Brachyury, were verified in the sphere formation assays of chordoma cell lines." (PMID 40135815, 2025). "In the RAB3B‐small‐interfering RNA (siRNA)‐treated chordoma cells, mRNA and protein levels of chordoma stemness markers (TBXT, NANOG, OCT4, and SOX2) were significantly decreased." (PMID 40135815, 2025). "To evaluate the roles of other RAB3 members in the chordoma stemness and tumorigenic functions, we found that RAB3A, RAB3C, and RAB3D regulated the proliferation of CH22 cells, whereas they did not control the expressions of stemness markers, such as TBXT, NANOG, OCT4 and SOX2." (PMID 40135815, 2025).
Cirrhosis (2 papers, 2019 to 2020). A chronic disorder of the liver in which liver tissue becomes scarred and is partially replaced by regenerative nodules and fibrotic tissue resulting in loss of liver function. "SOX2 positivity was significantly associated with younger age (p<0.037), male gender (p< 0.006) and presence of cirrhosis (p<0.0001)." (PMID 33112555, 2020). "Both protein expression levels of TLR4 and SOX2 were significantly elevated in relapsed HCC samples when compared with the cirrhosis samples and unrelapsed HCC samples." (PMID 30957973, 2019). "We detected the expressions of TLR4 and SOX2 by immunohistochemistry in HCC primary lesion samples and cirrhosis samples." (PMID 30957973, 2019).
cleft palate (2 papers, 2019 to 2022). Cleft palate is a fissure type embryopathy that affects the soft and hard palate to varying degrees. "SOX2 is highly correlated with FOXE1, whose congenital mutations cause cleft palate and hypothyroidism." (PMID 30704473, 2019).
colorectal adenocarcinoma (2 papers, 2014 to 2022). The most common type of colorectal carcinoma. "In addition, METTL3 is reported to maintain SOX2 expression in an m6A-dependent mechanism to facilitate the progression of colorectal adenocarcinoma." (PMID 35217651, 2022).
diabetic nephropathy (2 papers, 2010 to 2023). "MCF2L2, ADIPOQ and SOX2 genes are located in chromosome 3q26-27, which is linked to diabetic nephropathy (DN)." (PMID 20667095, 2010). "CircASAP2 blocks miR-770-5p to enhance the expression of SRY-Box transcription factor 2 (SOX2) and then induces SLC7A11 expression to suppress ferroptosis in diabetic nephropathy." (PMID 37686142, 2023).
diffuse intrinsic pontine glioma (2 papers, 2022 to 2023). A neuroglial tumor that arises from the middle portion of the brain stem. "In diffuse intrinsic pontine glioma, super-enhancers are found at the loci of a number of genes indicating undifferentiation status such as SOX2 and NES as well as oncogenes such EGFR." (PMID 38135679, 2023). "The authors also showed that the BMP4 treatment of diffuse intrinsic pontine glioma (DIPG) cells induced a stemness blockade accompanied by decreased SOX2 and OLIG2 expression, further validating our findings." (PMID 36497175, 2022). "Similarly, in diffuse intrinsic pontine glioma, the expression of critical oncogenic genes such as SOX2 and NOTCH1 is regulated by super-enhancers, and treatment with super-enhancer inhibitors reduces diffuse intrinsic pontine glioma cell proliferation in vitro and tumor progression in mouse models." (PMID 38135679, 2023).
Duchenne muscular dystrophy (2 papers, 2018 to 2021). Duchenne muscular dystrophy (DMD) is a neuromuscular disease characterized by rapidly progressive muscle weakness and wasting due to degeneration of skeletal, smooth and cardiac muscle. "The DYS-HAC was transferred to Duchenne muscular dystrophy patient-derived fibroblasts from CHO cells, from which iPSCs were generated using a combination of lentiviral infection for expressing mouse SLC7A1 and retroviral infection for expressing KLF4, SOX2, OCT4, and c-MYC." (PMID 32161806, 2018).
endometrial adenocarcinoma (2 papers, 2018 to 2020). "Reported nuclear OCT-4 and SOX2 in endometrial adenocarcinoma tissue." (PMID 30241552, 2018).
epithelioid sarcoma (2 papers, 2024). An aggressive malignant neoplasm of uncertain differentiation, characterized by the presence of epithelioid cells forming nodular patterns. "However, epithelioid sarcoma is SMARCB1-deficient with retained SMARCA2 expression, and the expression of SOX2 and SALL4 is deficient." (PMID 38347129, 2024). "The loss of SMARCA4 (BRG-1) can exceptionally occur in tumors such as SMARCB1/INI1-retained epithelioid sarcoma (ES); in this context, the absence of SOX2 and SALL4 expression aids in distinguishing ES from SMARCA4-UT." (PMID 38265099, 2024).
Feingold syndrome (2 papers, 2011 to 2022). Feingold syndrome (FS), also known as oculo-digito-esophageal-duodenal (ODED) syndrome, is a rare inherited malformation syndrome characterized by microcephaly, short stature and numerous digital anomalies and is comprised of two subtypes: FS type 1 (FS1) and FS type 2 (FS2). "In fact Pax is located in chromosome 11p13, Foxd11 on 5q12-13, Mycn (producing Feingold syndrome) on 2p24.1, Chd7 (CHARGE) on 8q12.2 and Sox2 (AEG) on 3q26." (PMID 21806818, 2011).
ganglioglioma (2 papers, 2018 to 2023). A well differentiated, slow growing neuroepithelial neoplasm composed of neoplastic, mature ganglion cells and neoplastic glial cells. "Co-expression of CD34, PAX6, SOX2, and MSI1 (after stringent counter selection against vascular cells using PECAM1, VWF, DCN, and COL1A2), was particularly strongly associated with ganglioglioma neoplastic cell stemness." (PMID 36966348, 2023). "In ganglioglioma controls, Tbr1 nuclear labelling of dysmorphic neurons was noted in one case; a variable proportion also showed cytoplasmic OTX1 positive labelling but more consistent labelling was observed with SOX2." (PMID 28833756, 2018).
germinoma (2 papers, 2013 to 2023). A malignant germ cell tumor arising in the central nervous system. "However, it has been widely accepted that germinoma is a prototype of all GCTs, by CSC markers of Oct4, Nanog, SOX17 (germinoma), SOX2 (infantile GCTs), and differentiation markers of PLAP and KIT (germinoma differentiation markers from ES cells, rare in intracranial none germinoma GCTs (NGGCTs))." (PMID 37370764, 2023).
gestational trophoblastic disease (2 papers, 2010 to 2013). "In a previous study of methylation status of SOX2 in gestational trophoblastic diseases, we identified a CpG island upstream of the transcription start site of SOX2." (PMID 20814443, 2010).
hamartoma (2 papers, 2023). A benign and excessive tumor-like growth of mature cells and normal tissues which grow in a disorganized pattern. "Moreover, hamartomas expressed and retained elevated Sox2, a marker of neuroprogenitors." (PMID 38107199, 2023).
holoprosencephaly (2 papers, 2020). Holoprosencephaly (HPE) is a complex brain malformation resulting from incomplete cleavage of the prosencephalon, occurring between the 18th and 28th day of gestation, and affecting both the forebrain and face, which results in neurological manifestations and facial anomalies of variable severity. "Mice overexpressing ShhN (Sox2-Cre;Shh+/+;ShhN or Sox2-Cre;ShhF/F;ShhN) exhibit polydactyly, holoprosencephaly, and cleft palate due to the long-range spread and activation of Shh signaling." (PMID 33256181, 2020).
hypopharyngeal squamous cell carcinoma (2 papers, 2010 to 2023). "The aim of this study was to examine the association between Oct4 and Sox2 expression levels with both the clinicopathological characteristics and prognoses of patients with hypopharyngeal squamous cell carcinoma." (PMID 20937145, 2010). "Simultaneous analyses of Oct4 and Sox2 expression could be more effective in evaluating the prognoses of patients with hypopharyngeal squamous cell carcinoma." (PMID 20937145, 2010). "Tumor tissue samples from 85 patients with hypopharyngeal squamous cell carcinoma were collected, and the clinical follow-up data of these patients were recorded, and expression status of Oct4 and Sox2 were examined in these tissue samples by immunohistochemistry (IHC)." (PMID 20937145, 2010). "Sox2 expression could be a potential prognostic predictor for patients with hypopharyngeal squamous cell carcinoma." (PMID 20937145, 2010). "However, the roles of Oct4 and Sox2 in hypopharyngeal squamous cell carcinoma still require further investigation." (PMID 20937145, 2010).
large cell lung cancer (2 papers, 2010 to 2012). "We found that SOX2 mRNA levels are significantly higher in lung SCCs relative to adenocarcinomas or large-cell lung carcinomas from various published microarray datasets." (PMID 20161759, 2010). "The same regulatory effects of SOX2 on the expression of WNT1, WNT2, NOTCH1 and c-MYC were also observed in the human large cell lung carcinoma cell line H460 with SOX2 silencing.This finding indicates a universal regulatory mechanism of SOX2 on the oncogene network of both human lung cell lines." (PMID 22615765, 2012).
laryngeal tumors (2 papers, 2018 to 2020). "In contrast, positive SOX2 expression was significantly more frequent in laryngeal tumors (p = 0.002)." (PMID 32635524, 2020). "While either NANOG expression or double-positive expression of NANOG and SOX2 were significantly correlated with improved survival rates in patients harboring pharyngeal tumors, none of these factors showed any impact on the clinical outcome of patients with laryngeal tumors." (PMID 32635524, 2020). "Thus, NANOG expression, and to a lesser extent SOX2, specifically predicted good prognosis in patients with pharyngeal but not laryngeal tumors." (PMID 32635524, 2020).
liver disease (2 papers, 2020 to 2023). "Collectively, previous reports and our results revealed that over-expression of SOX2 may lead to the development of liver diseases." (PMID 32121397, 2020). "We suggested that SOX2 may act as a restriction factor to repress HBV replication, not only during the acute infection, but also in the chronic infection and the development of liver diseases." (PMID 32121397, 2020). "By contrast, control CD133-/CD49f- cells expression levels for KRT19, CD133, NANOG, SOX2, OCT4, and TLR4 were independent of IVIG (immune serum from people with HBV+ or HCV+ liver disease) or HBIG incubation." (PMID 37744383, 2023).
Microcornea (2 papers, 2013 to 2022). A congenital abnormality of the cornea in which the cornea and the anterior segment of the eye are smaller than normal. "More importantly, we reveal that missense mutation in SOX2 can cause a slight eye disorder, that is congenital cataract and microcornea, warranting further investigations on the pathogenesis of this disorder." (PMID 35148715, 2022). "A novel missense mutation (c.295G > T, p.Ala99Ser) in the SOX2 gene was found in this Han Chinese family with congenital cataract and microcornea." (PMID 35148715, 2022). "The phenotype of associated microcornea may be due to the induction of corneal effects by an abnormally formed lens during embryonic development and/or a reduction of SOX2 on corneal molecular chaperones." (PMID 35148715, 2022). "Interestingly, a missense mutation in this study, SOX2 c.295G > T p.Ala99Ser, caused a slight phenotype: microcornea and cataract." (PMID 35148715, 2022).
monoclonal gammopathy of undetermined significance (2 papers, 2011 to 2014). "The occurrence of SOX2-specific autoantibodies seems to be associated with an improved prognosis in patients with monoclonal gammopathy of undetermined significance (MGUS)." (PMID 22190969, 2011). "In patients with monoclonal gammopathy of undetermined significance (MGUS), anti-SOX2 T cell responses were found to be directed against a very small percentage of tumor cells which were of the clonogenic type." (PMID 24940116, 2014).
Nephropathy (2 papers, 2010 to 2024). A nonspecific term referring to disease or damage of the kidneys. "To verify the potential roles of SOX2 in renal disease, we conducted correlation analysis and subgroup analysis between SOX2 and clinical features using the Nephroseq v5 online tool." (PMID 38617751, 2024). "The results showed that the mRNA expression of SOX2 was positively correlated with renal disease." (PMID 38617751, 2024).
neural neoplasms (2 papers, 2015 to 2022). "Neural tumors in particular were among the first tumors in which CSC/TIC were demonstrated, and these cells were shown to express SOX2." (PMID 35626641, 2022). "In this study, we show that neural stem/progenitor cells labeled by Sox2, Musashi1, nestin, CD133 or beta-tubulin antibodies accumulate at the borders of primary CNS B cell non-Hodkin lymphomas (NHL-CNS) and of metastatic non-neural neoplasms in the brain." (PMID 25713758, 2015).
oral disorders (2 papers, 2019 to 2023). "Among these, SOX2 has been found overexpressed along the different stages of oral carcinogenesis, from potentially malignant oral disorders to invasive carcinomas." (PMID 38096163, 2023).
ovarian endometriosis (2 papers, 2014 to 2018). A non-neoplastic disorder characterized by the growth of endometrial tissue in the ovaries. "In reproductive-age women with ovarian endometriosis, the transcriptional factor SOX2 and NANOG are over expression." (PMID 24884521, 2014). "SOX2 mRNA expression in the eutopic endometrium of ovarian endometriosis were significantly higher than that in normal endometrium (P = 0.02); expression of NANOG and OCT4 mRNA in eutopic endometrium increased but no statistically significant when compared with normal controls." (PMID 24884521, 2014). "SOX2, NANOG, and OCT4 protein were mainly expressed in the nuclei of glandular epithelial or stromal cells of ectopic and eutopic endometrium of ovarian endometriosis and normal control endometrium, with low expression detected in the cytoplasm of both cell types." (PMID 24884521, 2014). "We aimed to analyze the transcription pluripotency factors sex-determining region Y-box 2 (SOX2), Nanog homeobox (NANOG), and octamer-binding protein 4 (OCT4) in the endometrium of reproductive-age women with and without ovarian endometriosis." (PMID 24884521, 2014). "Therefore, we aimed to examine and compare SOX2, NANOG, and OCT4 expression in endometrial or endometriotic tissues from women with and without ovarian endometriosis." (PMID 24884521, 2014).
papilloma (2 papers, 2016 to 2022). A benign epithelial neoplasm that projects above the surrounding epithelial surface and consists of villous or arborescent outgrowths of fibrovascular stroma. "Sox2 expression was also observed in murine papillomas (analogous to human AKs) and cSCCs tumors that were induced using the chemical carcinogen 7,12-Dimethylbenz[a]anthracene/12-O-tetradecanoylphorbol 13-acetate (DMBA/TPA)." (PMID 35892887, 2022). "Deletion of Sox2 in established papillomas and cSCCs resulted in tumor regression." (PMID 35892887, 2022).
periodontitis (2 papers, 2019 to 2025). An acute or chronic inflammatory process that affects the tissues that surround and support the teeth. "Additionally, in experimental periodontitis by Gu & Ding, 2023, the miRNA-200c/SOX2 axis has been shown to modulate alveolar bone resorption via RANKL changes." (PMID 41176605, 2025).